TSPYL1 (TSPY like 1)
Synonyms: TSPYL
Tractability: PROTAC: UniProt records ubiquitination sites on it; ubiquitination databases record sites on it; its protein half-life has been measured.
Gene: Protein-coding gene on chromosome 6 (116,267,760 to 116,279,930, reverse strand). Ensembl gene ENSG00000189241.
Subcellular location: Nucleus, nucleolus
Subcellular location (Human Protein Atlas): Nucleoli; Nucleoplasm
Gene Ontology:
Molecular function: enzyme binding
Biological process: nucleosome assembly
Cellular component: nucleolus; nucleoplasm; chromatin; nucleus
Genetic constraint (gnomAD): Loss-of-function variants: 16 observed, 23.02 expected, observed/expected ratio (o/e) 0.7, 90% interval 0.47 to 1.06. The upper end of that interval is the gene's LOEUF score, 1.06, which puts it in group 4 of 6, group 1 being the genes least tolerant of losing a copy. Missense variants: 560 observed, 571.89 expected, observed/expected ratio (o/e) 0.98, 90% interval 0.91 to 1.05. Synonymous variants: 259 observed, 231.32 expected, observed/expected ratio (o/e) 1.12, 90% interval 1.01 to 1.24.
Homologues: Orthologues: chimpanzee TSPYL1 (99% identical), macaque TSPYL1 (95% identical), guinea pig TSPYL1 (61% identical), mouse Tspyl1 (60% identical), rat Tspyl1 (60% identical), pig TSPYL1 (59% identical), tropical clawed frog tspyl2 (31% identical), zebrafish tspy (24% identical), Drosophila melanogaster Set (18% identical), Caenorhabditis elegans spr-2 (16% identical), Drosophila melanogaster Nap1 (14% identical), zebrafish nap1l4a (11% identical), and 3 more. Paralogues in human: TSPYL6 (60% identical), TSPYL4 (53% identical), TSPYL2 (38% identical), TSPYL5 (37% identical), TSPY1 (24% identical), TSPY10 (24% identical), TSPY3 (24% identical), TSPY4 (24% identical), TSPY8 (24% identical), TSPY9 (24% identical), TSPY2 (24% identical), SETSIP (21% identical), and 6 more.
Diseases named in the same sentence as TSPYL1 in open-access papers:
TSPYL1 is named in the same sentence as 14 diseases in open-access papers, as found by Europe PMC text mining. Sharing a sentence is not in itself a finding about the gene and the disease. The quoted sentences say what the papers report.
glioma (1 paper, 2025). A benign or malignant brain and spinal cord tumor that arises from glial cells (astrocytes, oligodendrocytes, ependymal cells). "TSPYL1, a chromatin remodeling factor, is associated with neural development and may contribute to glioma progression, as identified in IDH1-associated tumor evolution studies." (PMID 40725410, 2025).
lung carcinoma (1 paper, 2024). "Depletion of TSPYL2 rescues the EMT phenotype of TSPYL1 knockdown in A549 lung carcinoma cells." (PMID 38588050, 2024).
major depressive disorder (1 paper, 2025). An episode of depression lasting two or more weeks without an intervening episode of mania. "Additionally, PTPN6, STIP1, ANPEP, and TSPYL1 were found to be correlated with major depressive disorder." (PMID 40520536, 2025).
Obesity (1 paper, 2022). Accumulation of substantial excess body fat. "Since TSPYL1 knockdown in hepatic cells resulted in increased CYP1B1 and decreased CYP7A1 expression, we asked whether TSPYL1 expression might be associated with obesity and/or plasma cholesterol concentrations in humans." (PMID 36518674, 2022). "Finally, we observed that TSPYL1 expression was associated with plasma cholesterol levels and BMI during previous clinical studies of obesity." (PMID 36518674, 2022). "As an initial step toward systematically testing the hypothesis that hepatic TSPYL1 expression might be associated with obesity, we examined publically available data from two clinical studies addressing obesity in which hepatic mRNA expression had been determined." (PMID 36518674, 2022). "Taken together, these results suggest that variation in TSPYL1 expression, Wnt/β-catenin signaling and CYP expression may all contribute to risk for or variation in response to the treatment of obesity." (PMID 36518674, 2022).
cancer (2 papers, 2019 to 2024). A tumor composed of atypical neoplastic, often pleomorphic cells that invade other tissues. "In our study, we uncover that TSPYL1 binds the promoter of TGFBR1 in a variety of cancer cell lines as well as normal cells." (PMID 38588050, 2024).
tumor (2 papers, 2016 to 2025). "For example, elevated expressions of CMTR1, TSPYL1, or RPL23AP42 are associated with poorer survival, aligning with their hypothesized roles in promoting tumor progression or interfering with gene regulation." (PMID 40725410, 2025).
TSPYL1 also shares sentences with these, for which no sentence is quoted: breast carcinoma (1 paper); breast ductal carcinoma (1); cervical cancer (1); Infertility (1); male infertility (1); melanoma (1); neuroblastoma (1); renal fibrosis (1).